ZWINT (ZW10 interacting kinetochore protein)
Diseases named in the same sentence as ZWINT in open-access papers (continued):
Sharing a sentence is not in itself a finding about the gene and the disease.
cancer (continued). "Previously, ZWINT was found to be related to chromosome instability, which promotes the occurrence and development of a variety of malignant tumors." (PMID 34852139, 2021). "The current study found that high Zeste White 10 interactor (ZWINT) expression is related to the poor prognosis of patients with a variety of cancers." (PMID 34852139, 2021). "Moreover, ZWINT is directly regulated by CDK1 in many cancer types, and related to cancer cell metastatic ability through CDK1/ZWINT-mediated epithelial-mesenchymal transition (EMT) process." (PMID 40591167, 2025). "While the specific roles of the kinetochore’s molecular components and their interactions remain largely undefined, increasing evidence indicates that ZWINT is often overexpressed in various human cancers, correlating with unfavorable clinical outcomes and early recurrence." (PMID 40591167, 2025). "Consistent with our previous hypothesis, the RT-qPCR data demonstrated that the expression of ZWINT in cancer tissues was much higher than that in the neighboring tissues." (PMID 37091844, 2023). "ZWINT has been demonstrated to diminish chromosomal stability during the development of cancer, indicating that it may function as an oncoprotein." (PMID 37091844, 2023). "PCR and immunohistochemistry results indicated that the expression levels of the ZWINT gene were considerably higher in NSCLC cancer tissues than that in the surrounding tissues, and the ZWINT gene may contribute to disease progression by increasing the epithelial-mesenchymal transition (EMT)." (PMID 37091844, 2023). "Furthermore, immune infiltration analysis suggested FAM111B/ZWINT could affect the development and prognosis of cancer by regulating the LUAD immune microenvironment." (PMID 35406786, 2022). "ZW10 interacting kinetochore protein (ZWINT) has been demonstrated to play a pivotal role in the growth, invasion, and migration of cancers." (PMID 40591167, 2025). "Through comprehensive pan-cancer analysis utilizing the GEPIA, UALCAN, and TCGA databases, we systematically evaluated ZWINT expression profiles." (PMID 40591167, 2025). "Cancer stage-wise expression analysis of the hub genes revealed that the expressions of TTK, BUB1B, and NUSAP1 increased while the expression of ZWINT decreased slightly with the stage-wise continued progression of OC." (PMID 37304238, 2023). "Conversely, some genes that displayed anti-HIV activity are known to be involved in signaling, both in various cancers (CD164, TNFRSF10A/D, ZWINT, MT1X, IL3) and immune or T cell activation (GBP5, CD1A)." (PMID 25980612, 2015). "This was indeed the case, as the list of genes exclusively detected in cancer, including TRAF7, PRPS1, CDT1, and ZWINT, were previously reported as cancer marker genes." (PMID 20454660, 2010). "Other candidates included DDC, MANEA, ZWINT, while ERG and SERPINA3 were examples of genes scored with decreased expression in LNCaP compared to CD26+ cancer." (PMID 20021671, 2009). "In the case of new potential markers, the ZWINT and CONDENSIN I subunits NCAPH, SMC2, and SMC4 all showed similar expression levels displayed by markers in the first circuit, even sharing the same clustering of cancer types." (PMID 40430225, 2025). "Therefore, to the best of our knowledge, this study is the first to report the probable cancer-driving role of the hsa-mir-124-3p miRNA with respect to TTK, BUB1B, NUSAP1, and ZWINT hub genes in OC." (PMID 37304238, 2023). "Furthermore, the immunohistochemical staining results based on the HPA database revealed a significantly high positivity of the ZWINT, RRM2, NDC80, KIF4A, CEP55, CENPU, and CENPF genes in cancer tissues compared to adjacent normal tissues." (PMID 35028418, 2022). "FAM111B, ZWINT and CDK1 have been shown to play important roles in the development of many cancers." (PMID 35406786, 2022).
cancer (continued). "At the same time, the deletion of ZWINT made the cells stay in G2/M phase, and the chromosome segregation process could not be performed, which increased the apoptosis of cancer cells." (PMID 35406786, 2022).
adenocarcinoma (1 paper, 2024). A common cancer characterized by the presence of malignant glandular cells. "Changes in SERPINE1, CDK1, ZWINT, and FN1 expression were validated using qRT-PCR after HMGB1 silencing or overexpression in PC-3 and LNCaP (selected as an adenocarcinoma model of PCa responding to hormonal treatment) cell lines." (PMID 38542079, 2024).
ZWINT also shares sentences with these, for which no sentence is quoted: colon cancer (3 papers); breast invasive carcinoma (2); triple-negative breast carcinoma (2); breast tumors (1); ductal breast carcinoma (1); Fanconi anemia (1); hepatitis B (1); Infertility (1); infiltrating ductal carcinoma (1); intraductal cribriform breast adenocarcinoma (1); invasive ductal and lobular carcinoma (1); invasive lobular breast carcinoma (1); lobular carcinoma (1); medullary carcinoma (1); Miscarriage (1); mucinous carcinoma (1); nasopharyngeal carcinoma (1); peripheral nerve injury (1); preeclampsia (1); Roberts syndrome (1); schizophrenia (1); thyroid carcinoma (1).